GCGR (glucagon receptor)
Diseases named in the same sentence as GCGR in open-access papers (continued):
Sharing a sentence is not in itself a finding about the gene and the disease.
type 2 diabetes (continued). "Thus, due to its fundamental role in promoting hepatic glucose production, therapeutic strategies aimed at both activating the GCGR to acutely rescue from hypoglycemia and at blocking glucagon-mediated hyperglycemia for the treatment of type 2 diabetes (T2D) have been pursued." (PMID 35547006, 2022). "Furthermore, there have been multiple attempts to produce glucagon receptor antagonists, since the high glucagon levels observed in type 2 diabetics may contribute to hyperglycemia." (PMID 32382023, 2020). "However, concerns about safety, tolerance, and stimulation of adverse immune response when using these types of agents against GCGR for the treatment of type 2 diabetes have led to investigations to identify drugs or compounds of natural origin to combat this problem." (PMID 26236379, 2015). "Indeed, GCGR antagonist/inhibitors of natural origin may be safe and favorable therapeutic agents for the treatment of type 2 diabetes." (PMID 26236379, 2015). "This is consistent with the clinical finding that treatment with glucagon receptor antagonists increased plasma LDL, HDL, and TG concentrations in individuals with type 2 diabetes." (PMID 39985139, 2025). "GLP-1R, glucagon receptor (GCGR) and glucose-dependent insulinotropic polypeptide receptor (GIPR) are validated therapeutic targets for type 2 diabetes and obesity." (PMID 38346960, 2024). "Two daily dose GLP-1 and glucagon receptor dual agonists, MEDI0382 and SAR425899, had been evaluated in overweight or obese patients with type 2 diabetes." (PMID 34430840, 2021). "Furthermore, as glucagon receptor antagonism may result in dyslipidemia, hyperaminoacidemia and hepatic lipid deposition, it has been suggested that glucagon agonism may be of therapeutic relevance for treatment of type 2 diabetes." (PMID 31284506, 2019). "The human glucagon receptor (GCGR), which belongs to one member of class B G-protein-coupled receptors (GPCRs), is a potential drug target of type 2 diabetes." (PMID 31921774, 2019). "Paralogous protein receptors in glucagon-like subfamily, glucagon receptor (GCGR) and glucagon-like peptide-1 receptor (GLP-1R), exhibit divergence in ligands and are clinically validated drug targets for type 2 diabetes." (PMID 28642113, 2017). "Glucagon receptor (GCGR) and glucagon-like peptide-1 receptor (GLP-1R), two clinically validated drug targets in patients with type 2 diabetes, were used as an example for functional divergence analysis." (PMID 28642113, 2017). "Similarly, knocking out GCGR and treatment with GCGR antagonist (LY2409021) induced liver fat accumulation in zebrafish and patients with type 2 diabetes (T2D), respectively." (PMID 33520988, 2020). "Moreover, a stable GCGR knockdown mouse colon cancer cell line, CMT93, grew significantly slower than control in a syngeneic mouse model of type 2 diabetes with glycemia and hyperglucagonemia." (PMID 29535833, 2018). "Furthermore, GCGR knockdown abolished the glucagon-mediated deactivation of AMPK and activation of MAPK, resulting in induction of an inhibitory effect of tumor growth in type 2 diabetes model mice." (PMID 29535833, 2018). "Notably, GCGR mAb induced a remarkable increase in islet number (db/db 1.6±0.1 vs 0.8±0.1 per mm2, p<0.001; HFD+STZ 1.2±0.1 vs 0.5±0.1 per mm2, p<0.01) and islet area (db/db 2.5±0.2 vs 1.2±0.2%, p<0.001; HFD+STZ 1.0±0.1 vs 0.3±0.1%, p<0.01) in the two mouse models of type 2 diabetes." (PMID 36331598, 2023). "However, administration of a glucagon receptor antagonist (GRA) does not seem to affect postprandial glucose excursions in patients with type 2 diabetes, indicating that glucagon is important for glucose homeostasis in the fasting state rather than postprandially." (PMID 31284506, 2019).
Hyperglycemia (53 papers, 2011 to 2025). An increased concentration of glucose in the blood. "This dual mechanism enhances weight reduction while minimizing the risk of hyperglycemia seen with glucagon receptor activation alone." (PMID 41153573, 2025). "Although long-term GCGR is linked to hyperglycemia and glucose intolerance (and thus antagonistic to insulin signaling), acute GCGR potentiates glucose metabolism and insulin sensitivity by a mechanism that involves hepatic rictor/mTORC2 and Akt signaling." (PMID 38270460, 2024). "For example, in addition to Gly40Ser, homozygous missense mutations (P86S) have been found in GCGR; these mutations contribute to the formation of an ineffective GCGR, resulting in hyperglycemia and extreme α-cell proliferation." (PMID 35784565, 2022). "The major targets of glucagon are hepatocytes on which glucagon receptors (GcgRs) are prevalent, but GcgRs are also expressed on β cells and GcgR null mice are resistant to β-cell loss and hyperglycemia." (PMID 21283589, 2011). "Impaired GCGR signaling could disrupt these regulatory axes, thus contributing to hyperglycemia and insulin resistance—2 conditions associated with cognitive decline and dementia—as well as metabolic dysregulation." (PMID 40271226, 2025). "Therefore, concurrent agonism at the GLP-1R and GCGR is important for the glucose-lowering effect of OXM: GLP-1R activation offsets the hyperglycaemia associated with GCGR activation." (PMID 34566894, 2021). "The results indicated that treatment with either the glucagon receptor mAb or GABA alone mitigated hyperglycemia and increased insulin levels by regenerating beta cells." (PMID 39594662, 2024). "In contrast to mice with congenital GCGR−/−, mice with an inducible GCGR−/− knockdown treated with STZ have only partial protection from hyperglycaemia." (PMID 38579751, 2024). "Treatment with GABA or the GCGR mAb individually improved hyperglycemia and increased β-cell mass, with similar effects observed in the combination treatment." (PMID 39057094, 2024). "A GLP-1 receptor blockade markedly attenuated the effect of a GCGR blockade to reduce hyperglycemia and EGP in STZ-induced diabetic mice as well as in db/db mice." (PMID 38265288, 2024). "The use of a GCGR antagonist molecule in the db/db diabetic mouse model and in diabetic mice induced by a high-fat diet and streptozotocin improved hyperglycemia and promoted beta-cell regeneration." (PMID 39120275, 2024). "In mouse models, there is evidence that treatment with glucagon receptor antibodies can reverse hyperglycemia through mechanisms such as alpha-to-beta cell trans-differentiation." (PMID 39594662, 2024). "Anti-GCGR treatment effectively reverses hyperglycemia, elevates plasma insulin levels, and restores β-cell mass through both β-cell proliferation and α-to-β-cell transdifferentiation." (PMID 39057094, 2024). "Increasing studies propose that blocking glucagon and/or GCGR can reduce hyperglycemia (for review see 165, 167)." (PMID 37008937, 2023). "GCGR antagonism ameliorated hyperglycemia and promoted β-cell regeneration in db/db mice and high-fat diet and streptozotocin-induced mice with T2D." (PMID 37008937, 2023). "As such, rebound hyperglycaemia has been observed on treatment termination with some small molecule GCGR antagonists, likely because of their actions to elevate circulating glucagon." (PMID 36005280, 2022). "IBI362 has been designed to balance the activation of GLP-1 receptor and glucagon receptor in order to avoid the glucagon receptor-induced hyperglycaemia while maintaining the desired effects of HbA1c reduction and body weight loss." (PMID 35750681, 2022). "Mazdutide was designed to balance the activation of GLP-1 receptor and glucagon receptor in order to avoid the glucagon receptor-induced hyperglycaemia while maintaining the desired effects of HbA1c reduction and body weight loss." (PMID 36247927, 2022).
Hyperglycemia (continued). "Given that efforts to develop pharmacological inhibitors of glucagon receptor signaling as a therapy for hyperglycemia in T2DM continue, it is critical to understand the potential consequences of blocking glucagon receptor signaling at the adipocyte." (PMID 36002172, 2022). "The same group further assessed various ratios of GCGR to GLP-1R potency of their peptides, on the extent of weight loss while minimising hyperglycaemia." (PMID 34566894, 2021). "For example, knockout of the glucagon receptor or using a monoclonal antibody against the glucagon receptor have been reported to improve hyperglycemia in an insulin-independent manner." (PMID 33839150, 2021). "IBI362 has been designed to balance the activation of GLP-1 receptor and glucagon receptor in order to avoid the glucagon receptor-induced hyperglycaemia while maintaining the desired effects of HbA1c-lowering and body weight reduction." (PMID 34430840, 2021). "The first question was to show how the glucagon receptor internalization leads to tolerance against glucagon-induced hyperglycemia." (PMID 31571122, 2019). "Here, we injected C57BL/6 mice with two different high doses of STZ that triggered a severe hyperglycemia; after anti-GCGR mAb treatment, however, we observed a decrease in glycemia only in animals treated with the lowest STZ dose." (PMID 27092792, 2016). "Here, we show that Gcgr-/- and anti-GCGR mAb-treated animals develop severe hyperglycemia after massive DT-mediated β-cell ablation." (PMID 27092792, 2016). "In particular we observed that i) anti-GCGR mAb administration reduced hyperglycemia in C57BL/6 mice treated with the lowest STZ dose and ii) S961 treatment caused a less severe increase in glycemia in Gcgr-/- than in Gcgr+/- animals." (PMID 27092792, 2016). "Blockage of the glucagon receptor seems to be effective in preventing GC-induced hyperglycemia and represents a potential mechanism for the treatment of hyperglycemia induced by GC treatment." (PMID 24705399, 2014). "It has previously been demonstrated that ASOs specific to the glucagon receptor (GCGR) transcript reduce its expression in liver improving hyperglycemia and hyperlipidemia." (PMID 25334092, 2014). "Clinical studies showed that GCGR antagonism significantly reduced hyperglucagonemic stimuli-induced hyperglycemia in humans." (PMID 23316165, 2012). "Key evidence includes the observation that mice lacking the GCGR do not develop hyperglycemia despite insulin deficiency, and that hyperglucagonemia is consistently observed across all forms of diabetes in humans." (PMID 41149695, 2025). "Furthermore, chronic hyperglycemia has been shown to upregulate hepatic GCGR expression while simultaneously impairing downstream signaling, indicating the development of hepatic glucagon resistance." (PMID 41149695, 2025). "Blocking the action of glucagon with a monoclonal antibody of GCGR (Ab-4) improved hyperglycemia." (PMID 39120275, 2024). "Furthermore, due to its dual agonist properties, Mazdutide can counteract the hyperglycemia caused by the GCGR by balancing the activation of GLP-1 and GCGR, hence preserving the desired effects of hemoglobin A1c (HbA1c) and weight loss." (PMID 38440786, 2024). "In addition, a GCGR antagonist reduced hyperglycemia accompanied by blunting of the increased ALT/ALT2 activity in mice." (PMID 37764697, 2023). "However, hyperglycaemia was clearly apparent in all GCGR antagonist-treated HFF-STZ mice by day 18, treatment intervention appeared to delay onset." (PMID 36005280, 2022). "Despite these beneficial effects, GCGR monoagonism induces hyperglycemia, which diminishes utility." (PMID 33411693, 2021). "The well-known phenotype of GCGR knockout mice, which are highly resistant to hyperglycaemia and show other metabolic abnormalities, may introduce additional challenges." (PMID 33933675, 2021).
Hyperglycemia (continued). "APD-elevated glucagon may therefore drive the hyperglycemic states that these drugs produce since glucagon receptor KO mice are protected against APD-induced hyperglycemia independently of changes in insulin levels." (PMID 33589583, 2021). "This study demonstrated the importance of combined GLP-1R and GCGR signalling, as administration of the balanced co-agonist to Glp1r-/- mice led to hyperglycaemia, further demonstrating the necessity of GLP-1R and GCGR co-agonism to minimise this predicted side-effect." (PMID 34566894, 2021). "Treatment with DualAG (protease‐resistant dual GLP1R/GCGR agonist) in a mouse model showed improvement in glucose tolerance in diet‐induced obese mice without causing hyperglycaemia, unlike typical GCGR activation; all while inducing weight loss, steatosis attenuation and lipid‐lowering effects." (PMID 39495024, 2025). "Besides the significant weight loss effect demonstrated by the GLORY-1 study (NCT05607680), mazdutide has been shown to counteract the hyperglycemia induced by GCGR activation by adequately balancing the effects of GLP-1R and GCGR activation, overall reducing HbA1c levels and fasting glucose." (PMID 40004572, 2025). "Notably, studies using glucagon receptor–deficient (GCGR-/-) mouse models have demonstrated that inhibiting glucagon action can ameliorate hyperglycemia even in the absence of insulin." (PMID 40822953, 2025). "Consequently we investigated whether pharmacological GCGR agonism in a diet-induced obese model of chronic hyperglycaemia can alleviate the deleterious effects of high-fat diet on co-ordinated insulin secretion." (PMID 38677509, 2024). "Work characterizing the phenotype of Gcgr knockout mice and various therapeutic modalities targeting the glucagon-GCGR system to lower glucose in an array of preclinical rodent models produced results that supported discovering agents to block glucagon action as a way to reduce hyperglycemia." (PMID 35547006, 2022). "However, more recent studies have shown that blocking the glucagon receptor in absolute insulin deficiency does not prevent hyperglycemia, indicating that residual insulin signalling is required in order for glucagon receptor antagonism to be effective." (PMID 34659118, 2021). "Our findings suggest that sustained activation of the glucagon receptor does not lead to hyperglycemia." (PMID 37140984, 2023). "GcgR antagonist restored neutrophil migration, reduced CFU numbers in the peritoneal cavity and improved survival rate of diabetic mice after CLP procedure, however, the treatment did no alter hyperglycemia, CXCL1/KC plasma levels and blood neutrophilia." (PMID 34295325, 2021). "Thus, the alteration of EGP and glycemia by treatment with GCGR blockers may not provide definitive proof as to whether hyperglucagonemia plays a dominant role in the inappropriately elevated postabsorptive EGP and hyperglycemia in patients with T2DM." (PMID 38265288, 2024).
Hypoglycemia (14 papers, 2012 to 2025). A decreased concentration of glucose in the blood. "We reported previously that the knock-in mice bearing homozygous V369M substitution (equivalent to a naturally occurring mutation V368M in the human glucagon receptor, GCGR) led to hypoglycemia with improved glucose tolerance." (PMID 34002801, 2021). "When glucagon receptor antagonists are used for treating type 1 diabetes, plasma ghrelin concentrations increase to antagonize drug-induced hypoglycemia." (PMID 36235843, 2022). "Disruption of GCGR results in many metabolic alterations, including increased glucose tolerance, decreased adiposity, hypoglycemia, and pancreatic α-cell hyperplasia." (PMID 31979106, 2020). "We previously generated GCGR knockout zebrafish that display hypoglycemia, hyperglucagonemia, and compensatory α-cell hyperplasia, demonstrating that the function of glucagon signaling is at least partially conserved between humans and zebrafish." (PMID 31979106, 2020). "GCGR blockade has been demonstrated to induce hypoglycemia, hyperaminoacidemia, hyperglucagonemia, decreased adiposity, hepatosteatosis, and pancreatic α cells hyperplasia in organisms." (PMID 33520988, 2020). "A recent glucagon receptor agonist dasiglucagon which used in the management of hypoglycemia may be effective in preventing hypoglycemia and AD neuropathology." (PMID 38977507, 2024). "This is in line with studies on glucagon receptor knock-out mice, which have shown that an absence of glucagon action does not cause hypoglycemia." (PMID 37512487, 2023). "Beyond suppressing hyperglycemia, disruption of GCGR also leads to increased insulin sensitivity, hypoglycemia, hyperglucagonemia, hyperaminoacidemia, increased plasma LDL, increased GLP-1 and FGF21 levels, decreased adiposity, and hyperplasia of pancreatic α-cells in mouse models." (PMID 31979106, 2020). "For instance, volagidemab (REMD-477), a monoclonal antibody targeting GCGR, has been shown to reduce insulin requirements and lower mean daily glucose by approximately 27 mg/dL over 24 hours in individuals with type 1 diabetes, without increasing the risk of hypoglycemia." (PMID 40822953, 2025). "Neither approach to disruption of GCGR function results in overt hypoglycemia; this suggests that pharmacotherapy aimed at antagonizing glucagon action at the GCGR may provide useful reductions in blood glucose without significantly increasing risk for hypoglycemia." (PMID 23185367, 2012). "In a study with diabetic obese db/db mice, 83% reduction of glucagon receptor expression by antisense oligonucleotides did not induce hypoglycemia despite injection of exogenous insulin." (PMID 23744070, 2013). "In conclusion, human monoclonal antibody against GCGR significantly improved glucose homeostasis in diabetic mice by suppressing hepatic glucose output with no hypoglycemia or adverse events." (PMID 23226550, 2012). "In addition, blocking the interaction between ghrelin and/or ghrelin receptors aggravated hypoglycemia symptoms, which suggests that ghrelin may be a good combination agent for patients who do not respond well to glucagon receptor antagonists." (PMID 36235843, 2022).
dyslipidemia (10 papers, 2019 to 2025). "Our data show that female mice with genetic deletion of the glucagon receptor are prone to steatosis and dyslipidemia when fed a GAN diet and HFD." (PMID 39985139, 2025). "Patients who were treated with glucagon receptor antagonists had dyslipidemia and increased hepatic fat." (PMID 39459592, 2024). "Given that glucagon receptor agonism can improve dyslipidemia and decrease hepatic lipid accumulation, it is critical to understand the tissue-specific effects of glucagon receptor action." (PMID 36002172, 2022). "Glucagon receptor agonists show promise as components of next generation metabolic syndrome pharmacotherapies." (PMID 34799628, 2021). "Glucagon receptor agonists combined with glucagon-like peptide 1 receptor agonists (dual agonists) improve dyslipidemia and reduce hepatic steatosis." (PMID 31068828, 2019). "Glucagon receptor antagonists have indirectly put focus on glucagon’s potential role in lipid metabolism, as individuals treated with these antagonists showed dyslipidemia and increased hepatic fat." (PMID 31284506, 2019). "Indeed, several bioactive peptides which include GCGR agonism as a deliberate component of their pharmacodynamic profile are being developed which show promise for the treatment of metabolic syndromes in humans." (PMID 34799628, 2021). "New strategies using these unimolecular polyagonists targeting the glucagon receptor (GCGR), have become successful approaches to evaluate the multifaceted nature of glucagon signaling in energy balance and metabolic syndrome." (PMID 31405212, 2019).